RN7SKP260 (RN7SK pseudogene 260)
Gene: Miscellaneous RNA gene on chromosome 2 (206,260,066 to 206,260,214, reverse strand). Ensembl gene ENSG00000252716.
Homologues: Orthologues: chimpanzee 7SK (97% identical), mouse Gm54737 (60% identical), guinea pig 7SK (58% identical). Paralogues in human: RN7SKP250 (76% identical), RN7SKP150 (75% identical), RN7SKP176 (74% identical), RN7SKP189 (74% identical), RN7SKP240 (73% identical), 7SK (72% identical), RN7SKP239 (72% identical), RN7SKP246 (72% identical), RN7SKP255 (72% identical), RN7SKP269 (72% identical), RN7SKP80 (72% identical), RN7SKP284 (72% identical), and 284 more.